GFAP (glial fibrillary acidic protein)
Diseases named in the same sentence as GFAP in open-access papers (continued):
Sharing a sentence is not in itself a finding about the gene and the disease.
leishmaniasis (1 paper, 2019). Infectious disease that is transmitted through the bite of hematophagous female phlebotomine sand flies. "Leishmaniasis induced significant increase of spinal cord GFAP, Iba-1, TNF-α, IL-1β, CX3CR1, and CX3CL1 mRNA expression, which were inhibited by α-aminoadipate, minocycline, and PDTC treatments (p < 0.05)." (PMID 31138231, 2019). "However, the role of spinal cord glial cells in regulating leishmaniasis-induced hyperalgesia does not seem to occur at all time points of infection since GFAP and Iba-1 mRNA expression peaked at the 30th day of infection." (PMID 31138231, 2019).
lumbar disk herniation (1 paper, 2018). "Moreover, to determine which cell types express IL-33 and ST2 in a rat model of noncompressive lumbar disk herniation, double staining was performed using anti-IL-33 or anti-ST2 antibodies and antibodies specific for neurons (NeuN), astrocytes (GFAP), microglia (OX-42), or oligodendrocytes (Olig-2)." (PMID 29329586, 2018).
Lymphatic Metastasis (1 paper, 2022). Transfer of a neoplasm from its primary site to lymph nodes or to distant parts of the body by way of the lymphatic system. "The mRNA level of GFAP was found to correlate with the occurrence of lymphatic metastasis in TGCT." (PMID 35454778, 2022). "However, GFAP was not identified as an independent factor for the occurrence of lymphatic metastasis in TGCT by multifactorial Cox regression analysis." (PMID 35454778, 2022).
malnutrition (1 paper, 2022). Inadequate nutrition resulting from poor diet, malabsorption, or abnormal nutrient distribution. "Malnutrition induced by low protein diet (PM) for 11 weeks or by food-added 0.4 g/kg MSG for 8 weeks into NF pups significantly elevated Glial Fibrillary Acidic Protein (GFAB) content in brain by 50% and 200%, respectively, in brain homogenate as revealed by ELISA results." (PMID 36015160, 2022).
memory (1 paper, 2022). The activities involved in the mental information processing system that receives (registers), modifies, stores, and retrieves informational stimuli. "It was proved that NP increases the expression of the glial fibrillary acidic protein (GFAP) as a specific astrocyte marker and as a result, it changed the morphological structure of astrocytes and causes apoptosis of neurons in the hippocampus, leading to learning and memory impairment." (PMID 35530167, 2022).
metastatic tumors (1 paper, 2025). "IF of paraffin sections of brain metastatic tumors in patients with LUAD further showed increased GFAP-positive astrocytes in the lesions of patients with low RBM10 expression." (PMID 40069781, 2025).
mononeuritis multiplex (1 paper, 2024). "In this study, GFAP tended to be inversely correlated with nervous system manifestations in AAV, though this association was weak and disappeared when certain minor items, such as peripheral neuropathy and mononeuritis multiplex, were excluded." (PMID 39459426, 2024).
morbid obesity (1 paper, 2026). An excess of body weight, normally defined as an individual with a body mass index greater than 35 or a body weight greater than one hundred percent of ideal body weight. "Thus, we assessed serum levels of neuron-specific enolase (NSE), transglutaminase 2 (TGM2), and glial fibrillary acidic protein (GFAP) as indirect markers of BBB dysfunction and examined their associations with steatosis severity, TNF-α and IL-10 in patients with morbid obesity." (PMID 42195075, 2026).
Multiple sulfatase deficiency (1 paper, 2022). "For example, it has been shown that astrocytic-specific deletion of Sulfatase Modifying Factor 1 (SUMF1) (Sumf1flox/flox; GFAP-Cre) was sufficient to induce neuron loss in a mouse model of multiple sulfatase deficiency (MSD)." (PMID 35444603, 2022).
nematode infection (1 paper, 2023). "GFAP and APP staining was not present in the brains of control mice, relatively weak in nematode-infected mice or mice given LPS and strongest in mice given both LPS and nematode infection." (PMID 37762297, 2023).
neuralgia (1 paper, 2020). "The western blotting results further reflect that GFAP, P2Y1R and p-JNK protein expression were increased in CCI group compared to sham group, indicating that a P2Y1R-dependent JNK pathway was drawn into CCI-induced neuralgia." (PMID 32365053, 2020).
Nocardia infection (1 paper, 2024). "The intestinal barrier permeability plus the Nocardia infection with higher levels of GFAP-positive cells may indicate that the infection delayed ileal healing, i.e., prolonged the period of inflammation." (PMID 38542396, 2024).
of the CNS (1 paper, 2015). "Furthermore, injury or disease of the CNS, such as AD, causes gliosis, which is characterized by activation of astrocytes and an increased expression of glial fibrillary acidic protein (GFAP) in these cells." (PMID 26697497, 2015).
Oncocytomas (1 paper, 2024). "Oncocytomas do not show positive staining for specific myoepithelial markers like smooth muscle actin, calponin, S-100 protein, and glial fibrillary acidic protein (GFAP)." (PMID 38817461, 2024).
optic pathway glioma (1 paper, 2019). Optic pathway glioma (OPG) is a benign tumor that develop along the optic nerve (chiasm, tracts, and radiations) characterized by impairment or loss of vision and may be accompanied by diencephalic symptoms such as reduced growth and alteration in sleeping patterns. "A conditional NF1 deletion in neuroglial progenitor cells (Nf1+/–GFAP conditional knockout mice) was originally developed to model optic pathway gliomas, but these mice also display attention and memory deficits that result from reduced striatal dopamine levels." (PMID 31600280, 2019).
osteoporosis (1 paper, 2024). A condition of reduced bone mass, with decreased cortical thickness and a decrease in the number and size of the trabeculae of cancellous bone (but normal chemical composition), resulting in increased fracture incidence. "Meanwhile, the expression of GFAP is also associated with the occurrence and progression of diseases such as osteoporosis." (PMID 38967699, 2024). "The results of Micro-CT observation showed that overexpression of GFAP further aggravated osteoporosis in DO rats while silencing GFAP alleviated osteoporosis in DO rats." (PMID 38967699, 2024). "MiR-15b-5p-GMNPE-EVs target GFAP to alleviate osteoporosis in DO rats." (PMID 38967699, 2024). "Compared with the miR-15b-5p-mimic-GMNPE-EVs + oe-NC group, further overexpression of GFAP increased the levels of CTX-I and TRAP 5b in DO rats, activating bone resorption and exacerbating osteoporosis." (PMID 38967699, 2024).
overnutrition (1 paper, 2023). An imbalanced nutritional status resulting from excessive intake of nutrients. "Overnutrition during pregnancy and lactation in mothers did not significantly alter the levels of GFAP in the prefrontal cortex in the offspring." (PMID 38201896, 2023).
Pain (1 paper, 2015). An unpleasant sensory and emotional experience associated with actual or potential tissue damage, or described in terms of such damage. "In conclusion, the results of this study show that animals with paclitaxel-induced neuropathic pain (PINP) have increased transcripts and immunoreactivity of the astrocyte marker GFAP and transcripts of some glutamate receptors and receptor subunits, but not glutamate transporters, in the ACC." (PMID 26528412, 2015).
pancreatic ductal adenocarcinoma (1 paper, 2024). An infiltrating adenocarcinoma that arises from the epithelial cells of the pancreas. "The presence of GFAP+ SCs has been documented in several malignancies, including pancreatic ductal adenocarcinoma (PDAC), a tumor that shares many similarities with CCA." (PMID 38474330, 2024). "It has been previously reported in pancreatic ductal adenocarcinoma, another model of cancer–glia interaction, that chains of GFAP+ SCs are implied in triggering PNI by actively recruiting cancer cells to transport them on nerve fibers." (PMID 38474330, 2024).
Parasitemia (1 paper, 2025). "Parasitemia, survival, and body weight were assessed, and brains were collected on day 9 p.i. for histopathological analysis (H&E staining) and GFAP immunohistochemistry." (PMID 40260212, 2025).
periodontitis (1 paper, 2023). An acute or chronic inflammatory process that affects the tissues that surround and support the teeth. "Ligature-induced periodontitis also increased Iba-1 immunoreactivity in the DG and thalamus regions as well as GFAP immunoreactivity in the thalamus region of 3 × Tg-AD mice." (PMID 36915108, 2023). "The observed changes in MT ratio also correlated significantly to Iba-1 immunoreactivity in the DG and GFAP immunoreactivity in the DG and thalamus region, indicating that periodontitis-induced glial responses may be responsible for the decreased MT ratio observed in 3 × Tg-AD mice." (PMID 36915108, 2023).
pertussis (1 paper, 2013). A contagious bacterial respiratory infection caused by Bordetella pertussis. "Other authors have demonstrated that a transgenic mouse that expressed CCL2 under the GFAP promoter developed pertussis-induced reversible inflammatory encephalopathy and that CCL2 directed a Th1-biased inflammatory reaction, as shown by high levels of TNF-α, INFγ and IL-2 in the CNS." (PMID 23866683, 2013).
photokeratitis (1 paper, 2019). Injury to the cornea secondary to ultraviolet light. "Thus, suppressive effects of fucoxanthin on pp38, TRPV-1 and GFAP may be important in avoid inflammatory pain following photokeratitis in the trigeminal ganglia." (PMID 30841522, 2019).
pineocytoma (1 paper, 2025). "In this case, histopathology confirmed both tumors, with synaptophysin and NSE positivity in the pineocytoma component and GFAP and OLIG2 positivity in the PA component; both showed a low proliferation index (Ki67 < 1%)." (PMID 40585941, 2025).
pituitary hormone deficiencies (1 paper, 2025). "Given its association with both new APH-D and new AVP-D, GFAP may be a more useful predictor of new pituitary hormone deficiencies following ETS for NFPA than tau or NfL." (PMID 41359198, 2025). "Elevated postoperative plasma GFAP, NfL, and tau might indicate increased risk of long-term postoperative pituitary hormone deficiency." (PMID 41359198, 2025).
pituitary tumor (1 paper, 2012). A benign or malignant neoplasm affecting the pituitary gland. "By using a transgenic over expression model, we show that GFAP-Cre mediated transgenic over expression of Bmi1 is sufficient to drive the formation of pituitary tumors, a type of tumor that represents 10 to 25% of all intracranial neoplasms in humans." (PMID 22574128, 2012). "The occurrence of pituitary tumors using GFAP-Cre mediated recombination of Rb has been shown before." (PMID 22574128, 2012). "We show here that Glial fibrillary acidic protein-Cre (GFAP-Cre) mediated conditional over expression of Bmi1 generates anterior and intermediate lobe pituitary tumors." (PMID 22574128, 2012).
Postural instability (1 paper, 2023). A tendency to fall or the inability to keep oneself from falling; imbalance. "Higher baseline plasma GFAP predicted a more rapid progression to postural instability (hazard ratio: 1.009, 95% CI [1.001–1.017], p = 0.033)." (PMID 37932720, 2023). "We explored if baseline plasma GFAP could predict progression to postural instability using the Kaplan–Meir survival analysis and Cox proportional hazards regression models." (PMID 37932720, 2023). "ROC analyses showed that a combination of baseline plasma GFAP levels and baseline UPDRS-III scores had a high accuracy (AUC: 0.824, 95% CI [0.740 to 0.909]) for distinguishing patients who would progress to postural instability within 5 years." (PMID 37932720, 2023).
prolactinomas (1 paper, 2023). "In prolactinomas, the co-expression of GFAP and cytokeratin was negatively correlated with disease recurrence of PT." (PMID 38187082, 2023).
prostatitis (1 paper, 2023). An infectious or non-infectious inflammatory process affecting the prostate gland. "Both glial markers Iba1 and GFAP were significantly overexpressed in the prostatitis group, and it was confirmed by ultrastructural changes in glial cells evident on electron microscopy." (PMID 37064799, 2023).
pseudorabies (1 paper, 2024). A highly contagious herpesvirus infection affecting the central nervous system of swine, cattle, dogs, cats, rats, and other animals. "GFAP down-regulation in the CNS has been associated with systemic inflammations due to infections, such as chronic infection with HIV-1, varicella zoster, and pseudorabies, as well as in astrocytes derived from iPSCs obtained from SAD and FAD patients." (PMID 38773640, 2024).
Pulmonary artery stenosis (1 paper, 2018). An abnormal narrowing or constriction of the pulmonary artery, in the main pulmonary artery and/or in the left or right pulmonary artery branches. "Mek1Y130C mutant mice exhibited pulmonary artery stenosis, cranial dysmorphia and neurological anomalies, including increased numbers of GFAP+ astrocytes and Olig2+ oligodendrocytes in regions of the cerebral cortex." (PMID 29590634, 2018).
radiculitis (1 paper, 2023). An inflammatory process affecting a nerve root. "While a direct link between GFAP-Abs and PNS involvement can be suggested in patients with sensory neuronopathy or demyelinating polyradiculoneuropathy, it is more difficult to explain such a link in patients with isolated cranial nerve involvement or radiculitis." (PMID 37540278, 2023).
rapid eye movement sleep behavior disorder (1 paper, 2024). "GFAP has the potential to differentiate between different subtypes of PD; plasma GFAP levels were significantly higher in patients with PD with rapid eye movement sleep behavior disorder (RBD) compared with patients the PD without RBD." (PMID 37815899, 2024).
renal dysfunction (1 paper, 2023). "Moreover, the behavioural changes might be related to changes in hippocampal BDNF and GFAP expression, which are common in renal dysfunction." (PMID 36420617, 2023).
retinal lattice degenerations (1 paper, 2020). "In this present study, retinal lattice degenerations were intraoperatively harvested from patients with rhegmatogenous retinal detachment, and were then used to perform immunostaining with GFAP, which is a glial cell marker, and CK and RPE65, which are retinal pigment epithelial markers." (PMID 33027920, 2020).
retinal tumors (1 paper, 2014). "In the Tg(flk1:RFP)is18 retinal tumors intense labeling of GFAP was detected extending throughout the tumor mass, indicating a glial cell type." (PMID 25485542, 2014). "Immunohistochemical analysis showed increased expression of the glial markers GFAP and BLBP throughout retinal tumors and in dysplastic optic nerve." (PMID 25485542, 2014). "In the Tg(flk1:RFP)is18 retinal tumors an increase in BLBP was detected throughout the tumor and did not appear to co-localize with GFAP positive Müller glia cells." (PMID 25485542, 2014).
retinal vein occlusion (1 paper, 2023). An occlusion of the retinal vein. "Proteins that were upregulated in our study and in experimental retinal vein occlusion included fibronectin, annexin A1, galectin-3, alpha-crystallin B chain, vimentin, annexin A2, STAT1, GFAP, osteopontin, vitronectin, and clusterin." (PMID 37175625, 2023).
rhabdoid tumor (1 paper, 2021). An aggressive malignant embryonal neoplasm usually occurring during childhood. "The LM F2T2↑ rhabdoid tumor showed a massive upregulation of a unique growth factor program with selectively activated Wnt and SHH/ciliogenesis pathways, and an intermediate filament expression switch, with GFAP loss, and peripherin and vimentin massive overexpression." (PMID 33853673, 2021).
Sandhoff disease (1 paper, 2021). A lysosomal disorder from the GM2 gangliosidosis family, caused by biallelic pathogenic variants in the HEXB gene, characterized by GM2 ganglioside accumulation in the nervous system and progressive central nervous system degeneration. "All Sandhoff disease model mice displayed GFAP-positive immunoreactivity in the cerebellum, consistent with previously reported GM2 ganglioside storage in this region and the consequent motor phenotype observed in these mice." (PMID 33919140, 2021).
Sensory neuropathy (1 paper, 2024). Peripheral neuropathy affecting the sensory nerves. "Astrocytic hyperplasia and high expression of the astrocyte activation marker protein glial fibrillary acidic protein (GFAP) are caused by systemic insulin resistance and sensory neuropathy." (PMID 38952685, 2024).
Skull Fractures (1 paper, 2016). Fractures of the skull which may result from penetrating or nonpenetrating head injuries or rarely BONE DISEASES (see also FRACTURES, SPONTANEOUS). "An intriguing observation arising from our study is that the concentrations of GFAP and UCH-L1 were highest in TBI subjects with ICI, but also increased in patients with a skull fracture and in those with a negative CT." (PMID 27319802, 2016).
somatoform disorder (1 paper, 2025). A category of psychiatric disorders which are characterized by the presence of physical symptoms that suggest a medical condition but are not fully explained by any known medical reasons. "BDNF, NfL and GFAP concentrations in serum and CSF were assessed in 106 treatment na﻿ïve patients with MS (pwMS) as well as 73 patients with other inflammatory/non-inflammatory neurological or somatoform disorders using a single molecule array HD-1 analyser." (PMID 39812717, 2025).
spastic ataxia (1 paper, 2010). "Thus, faced with a patient with progressive spastic ataxia, bulbar or pseudobulbar signs, and the typical tadpole on MRI, a genetic investigation of the GFAP gene is strongly recommended." (PMID 20359319, 2010).
Spastic paraparesis (1 paper, 2025). Partial loss of the ability to move the lower limbs accompanied by spasticity of the lower limbs. "Across studies, adult-onset AxD associated with GFAP mutations—including p/Gly18Val—is defined by slowly progressive spastic paraparesis, mild bulbar or cerebellar signs, and restricted medullary MRI changes with preserved supratentorial structures." (PMID 41303265, 2025).
Splenomegaly (1 paper, 2023). Abnormal increased size of the spleen. "The number or GFAP positive cells and Iba-1 positive cells were similar to controls and there was no sign of peripheral inflammation like splenomegaly, previously observed in C9orf72 knockout animals." (PMID 37138765, 2023).
steatosis (1 paper, 2026). Increased lipid within the cytoplasm of cells. "NSE and GFAP serum levels, but not TGM2, increased proportionally to steatosis stage, showing differences between severe steatosis and no steatosis (p = 0.012 and p = 0.0002, respectively)." (PMID 42195075, 2026).
stress-related disorder (1 paper, 2024). Stress-related disorders are mental health disorders that are a result of an atypical response to both short and long-term anxiety due to physical, mental, or emotional stress. "Post-mortem studies have also revealed decreased GFAP levels in brain regions such as the hippocampus, amygdala, and cerebellum in patients with stress-related disorders, further emphasizing its relevance in psychiatric pathology." (PMID 39796043, 2024).
toxoplasmosis (1 paper, 2015). A parasitic disease contracted by the ingestion or fetal transmission of toxoplasma gondii. "Immunohistochemistry was initially performed for glial fibrillary acidic protein (GFAP), MIB-1, CD45, CD68, CMV, and toxoplasmosis antigen." (PMID 26328586, 2015).
uremia (1 paper, 2019). A clinical syndrome associated with the retention of renal waste products or uremic toxins in the blood. "In our model, the elevated number of astrocytes observed within the ischemic cortex of uremic mice displayed both elevated GFAP expression and hypertrophic morphology, suggesting that uremia may have amplified the reactive astrogliosis." (PMID 31015533, 2019).